GCOM1 (GCOM1, MYZAP-POLR2M combined locus)
Synonyms: FLJ30973; GRINL1A; MYZAP-POLR2M; Gcom2; gcom
Gene: Protein-coding gene on chromosome 15 (57,591,908 to 57,714,745, forward strand). Ensembl gene ENSG00000137878.
Genetic constraint (gnomAD): Loss-of-function variants: 91 observed, 95.97 expected, observed/expected ratio (o/e) 0.95, 90% interval 0.8 to 1.13. The upper end of that interval is the gene's LOEUF score, 1.13, which puts it in group 4 of 6, group 1 being the genes least tolerant of losing a copy. Missense variants: 924 observed, 899.34 expected, observed/expected ratio (o/e) 1.03, 90% interval 0.97 to 1.09. Synonymous variants: 371 observed, 332.07 expected, observed/expected ratio (o/e) 1.12, 90% interval 1.02 to 1.22.
Diseases named in the same sentence as GCOM1 in open-access papers:
GCOM1 is named in the same sentence as 10 diseases in open-access papers, as found by Europe PMC text mining. Sharing a sentence is not in itself a finding about the gene and the disease. The quoted sentences say what the papers report.
prostate carcinoma (2 papers, 2014 to 2016). A carcinoma that arises from epithelial cells of the prostate gland. "Using this approach, the RIS were identified near a known prostate cancer gene PTRF as well as other genes that were not previously implicated in prostate cancer including ATPAF1, GCOM1, MEX3D, and TRPM4." (PMID 27792127, 2016).
Arrhythmia (1 paper, 2021). Any cardiac rhythm other than the normal sinus rhythm. "Of the six affected individuals with homozygous truncation in GCOM1, one had pacemaker (PM) and later heart transplantation, four suffered from ventricular and atrial arrhythmias, one had only ventricular arrhythmias, and one had no recorded arrhythmias but suffered SCD." (PMID 34899865, 2021).
cardiomyopathy (1 paper, 2021). A disease of the heart muscle or myocardium proper. "We identified two homozygous truncating GCOM1 variants, each in a different family, in patients presenting with cardiomyopathy." (PMID 34899865, 2021). "In this study, we describe the cardiac phenotypes of six cardiomyopathy patients with homozygous truncating GCOM1 variants from two families." (PMID 34899865, 2021). "A homozygous GCOM1 c.388C > T, p.(Arg130*) variant was observed in Family one in two DCM patients, and a homozygous GCOM1 c.1150 A > T, p.(Lys384*) variant was observed in Family two in four patients with cardiomyopathy." (PMID 34899865, 2021). "Two out of the four GCOM1 p.(Lys384*) homozygotes suffered from cardiomyopathy and died at young age, one fulfilled DCM diagnostic criteria, and one received a primary diagnosis of DCM, and later of ARVC." (PMID 34899865, 2021). "Our findings confirm the GCOM1 variants as a cause of human cardiomyopathy." (PMID 34899865, 2021). "GCOM1/MYZAP variants have not been published as a cause of human cardiomyopathy, but at least one variant has been reported in association with atrial arrhythmias." (PMID 34899865, 2021).
heart failure (1 paper, 2021). Inability of the heart to pump blood at an adequate rate to meet tissue metabolic requirements. "In broad panel testing, the patient’s parents (F1: I.1, I.2) were heterozygous for the GCOM1 variant, and did not have any other potentially pathogenic variants that could explain the heart failure in the daughter (II.4), who was homozygous for wildtype alleles in GCOM1." (PMID 34899865, 2021).
migraine (1 paper, 2025). "Burden testing identified several genes, including GCOM1, SETX, and SLC38A10, as significantly associated with HM, many of which have known roles in neurological function or migraine-related pathways." (PMID 40725463, 2025). "While a direct connection between GCOM1 and migraine has not yet been confirmed, its association with the ion channel NMDA receptors and the involvement of glutamate in migraine pathology present compelling possibilities." (PMID 40725463, 2025). "Specifically, GCOM1 interacts with the NR1 subunit of NMDA receptors, which play a pivotal role in migraine development, particularly in CSD, a key mechanism behind migraine aura." (PMID 40725463, 2025). "Considering GCOM1’s interaction with NMDA receptors, it may represent an understudied factor in the intricate genetic framework of the migraine." (PMID 40725463, 2025). "Although GCOM1 has not been directly studied in this context, its relationship with NMDA receptors implies it could indirectly influence migraine susceptibility." (PMID 40725463, 2025).
tumor (1 paper, 2014). "Promising candidates identified from the androgen-independent in vivo tumor were GCOM1 (GRINL1A complex locus 1), MEX3D (mex-3 RNA binding family member D), and PTRF (polymerase I and transcript release factor)." (PMID 24885513, 2014).
GCOM1 also shares sentences with these, for which no sentence is quoted: cancer (1 paper); migraine aura (1); Recessive Dilated Cardiomyopathy (1); Ventricular arrhythmia (1).